PIEZO2 (piezo type mechanosensitive ion channel component 2)
Diseases named in the same sentence as PIEZO2 in open-access papers (continued):
Sharing a sentence is not in itself a finding about the gene and the disease.
channelopathy (continued). "However, it is noteworthy that the exposure to methylmercury exerts its neurotoxicity in ALS through the overexpression of Restrictive Element 1 Silencing Transcription factor (REST) and Piezo2 channelopathy is proposed to be a principal transcription activator." (PMID 38534336, 2024). "However, this protective mechanism could derail under allostasis when mechanotransduction is prolonged excessively, and that is when Piezo2 channelopathy as a mechano-energetic microdamage may evolve." (PMID 38534336, 2024). "Hence, Piezo2 channelopathy on somatosensory terminals contributing to proprioception could not only activate the innate immune system through IL-6 but also activate the adaptive immune system in RA." (PMID 37108693, 2023). "Hence, the corneal Piezo2 channelopathy-induced impaired Piezo2-Piezo1 crosstalk could explain the disrupted neural regeneration." (PMID 37895134, 2023). "However, the Piezo2 channelopathy theory postulates that this gating machinery of Piezo2 could be microdamaged due to further prolonged excessive mechanotransduction under allostatic stress, leading to an influx of leakage subthreshold Ca2+ currents." (PMID 37895134, 2023). "Consequently, Piezo2 channelopathies could enhance this break function with simultaneous transcription activation, therefore, occluding the appropriate wound closure and healing." (PMID 36983813, 2023). "In addition, it is suggested that Piezo2 channelopathy is also a principal transcription activator." (PMID 37895134, 2023). "Furthermore, Piezo1 upregulation in activated keratocytes due to chronic Piezo2 channelopathy and impaired Piezo crosstalk could also lead to an imbalance in the Th17/Treg ratio, contributing to DED." (PMID 37108693, 2023). "Moreover, the current authors postulate that Piezo1 in activated corneal keratocytes could be upregulated in a feed-forward manner in DED, as was suggested in psoriasis, due to chronic Piezo2 channelopathy and impaired Piezo crosstalk." (PMID 37108693, 2023). "Therefore, DED could be initiated by a chronic Piezo1 channelopathy, but could also evolve into an NCP, which is considered primarily a Piezo2 channelopathy, constituting the nociceptive continuum paradox." (PMID 35507012, 2022). "In summary, this opinion piece postulates that the primary microinjury of our “sixth sense”, or the Piezo2 channelopathy of the somatosensory terminals contributing to proprioception, could be the principal gateway to pathology due to the encroachment of our preprogrammed genetic encoding." (PMID 36233237, 2022). "Indeed, C-fiber contribution is essential from eccentric exercised muscles in DOMS in order to provide the slow temporal summation, but must involve other factors than muscle damage, and that is suggested to be the microdamage of the Type Ia terminal, or, more precisely, the Piezo2 channelopathy." (PMID 35736014, 2022). "Accordingly, the author theorizes that the stress-induced impairment of prolonged static-phase firing and the Piezo2 channelopathy could lead to lost position control of cell orientation in the epidermis, as was hypothesized in the primary injury phase of DOMS." (PMID 36233237, 2022). "Notably, linoleic acid directly stabilizes Piezo2 protein–lipid interactions through its strong lipophilicity, blocking the TMEM120A/MyoD dissociation-induced proton leak pathway, thereby reversing acquired Piezo2 channelopathy-associated neurodegenerative injury." (PMID 41281194, 2025). "Consequently, the impaired Piezo2–Piezo1 crosstalk resulting from acquired Piezo2 channelopathy may lead to the abrogation of proper Piezo1 modulation, which could, in turn, result in insulin resistance, given that Piezo1 is involved in glucose-induced insulin secretion." (PMID 40137805, 2025).
channelopathy (continued). "In addition, the lost functional link of the MyoD family of inhibitor proteins, as auxiliary subunits of Piezo2, may not only contribute to the theorized acquired Piezo2 channelopathy, but may explain how these microinjured ion channels evolve to be principal transcription activators." (PMID 38534336, 2024). "Furthermore, the current authors suggest that the nerve growth factor (NGF)-tropomyosin receptor kinase A (TrkA) axis signaling plays a role in promoting the development of this dose-limiting and threshold-driven Piezo2 channelopathy that may explain the sex difference in the epidemiology of DED." (PMID 35507012, 2022). "Notably, these hallmark peripheral findings of psoriasis may already be part of the sensitization mechanism of the disease, mentioned later, and could reflect that “part of wound healing kept alive permanently”, at least partially due to chronic Piezo2 channelopathy." (PMID 36233237, 2022). "On the other hand, long-term dependence of the MC and other HRV parameters was described and interpreted as an age-related remodeling of the cardiac system, in line with the acquired Piezo2-channelopathy-induced quad-phasic non-contact injury model." (PMID 40863771, 2025). "Accordingly, it has been proposed that over-excessive axial compression forces induce the preceding neuromuscular disruption by instigating indentation on Piezo2, leading to Piezo2 channelopathy, prior to non-contact ACL injury occurrence." (PMID 41441398, 2025). "Correspondingly, a quad-phasic non-contact injury model was proposed as a result of Piezo2 channelopathy, emphasizing that Piezo2 microinjury is one principal gateway to pathophysiology." (PMID 36983813, 2023). "It is noteworthy that a functionally analogous autonomously acquired PIEZO2 channelopathy is proposed in DOMS and amyotrophic lateral sclerosis as well due to the dissociation of the auxiliary connection of the inhibitor protein ligands of PIEZO2, like MyoD or TMEM120A." (PMID 39682086, 2024). "It has been theorized that chronic Piezo2 channelopathy could shift the canonical Wnt signaling pathway toward noncanonical signaling pathway." (PMID 36233237, 2022). "Recently, it has even been suggested that overexcitation of Piezo2 on proprioceptive terminals under allostatic stress could dissociate accessory ligands, like MyoD-family inhibitor proteins or TMEM120A, leading to proton affinity switch-derived Piezo2 channelopathy." (PMID 41155507, 2025). "The current author is emphasizing the difference between two states, namely, that proprioceptive terminal hyperexcitation without leakiness leads to inactivation of Piezo2, as opposed to hyperexcitation with leakiness that could lead to pathology and transient Piezo2 channelopathy." (PMID 36139045, 2022). "The current paper puts into perspective that one gateway from physiology to pathophysiology could be a Piezo2 channelopathy, opening the pathway to a potentially quad-phasic non-contact injury mechanism on a multifactorial basis and with a heterogeneous clinical picture." (PMID 35507012, 2022). "In summary, the suggested primary damage in DED, namely the corneal mechanosensory Piezo2 channelopathy, is independent of SLE and disrupts neural regeneration on the chronic path by impairing the Piezo2–Piezo1 crosstalk." (PMID 37445856, 2023). "Moreover, the authors theorized that this corneal somatosensory-terminal Piezo2 channelopathy could evolve due to even noncontact mechanoenergetic corneal sensory-afferent damage crosslinked with underlying RA-derived spinal K2P-TASK1 signaling-axis activation." (PMID 37108693, 2023).
breast carcinoma (16 papers, 2019 to 2025). "In contrast, hypomethylation of Piezo2 was associated with a good prognosis for patients with kidney cancer, bladder cancer, and breast cancer." (PMID 35991548, 2022). "Downregulation of PIEZO-2 gene in breast cancer has been molecularly linked with estrogen and progesterone receptors which are responsible agents for Hh signaling cascade in breast cancer." (PMID 33489917, 2020). "Conversely, Piezo2 expression was found to be positively correlated with ER status but negatively correlated with triple-negative status in breast cancer, indicating that high expression of Piezo2 is strongly linked to progression of breast cancer." (PMID 32635333, 2020). "Recently, the other member of the Piezo family, Piezo2, has been implicated in the modulation of breast cancer cell migration." (PMID 32635333, 2020). "All these findings indicate that PIEZO2 might be associated with Hedgehog signaling pathway by regulating CDON in breast cancer." (PMID 31058608, 2019). "Next, we explored the underlying mechanism how PIEZO2 exerted its roles in breast cancer." (PMID 31058608, 2019). "Finally, we explored the underlying regulatory mechanisms of PIEZO2 in breast cancer." (PMID 31058608, 2019). "For example, in low-malignancy breast cancers, PIEZO2 potentially exerts a protective effect through CDON-Hedgehog axis-mediated induction of proapoptotic signaling, thereby suppressing tumor growth." (PMID 41327436, 2025). "Taken together, these findings underscore the bidirectional and subtype-dependent roles of PIEZO2 in breast cancer biology." (PMID 41327436, 2025). "Consistent with this pattern, transcriptomic and proteomic data indicate that PIEZO2 expression is generally downregulated in breast carcinoma relative to normal epithelium." (PMID 41327436, 2025). "Across breast cancer subtypes, PIEZO2 displays striking heterogeneity and context-specific behavior, reflecting the complex interplay between mechanotransduction and molecular signaling networks." (PMID 41327436, 2025). "In our experiment, a majority of breast cancer patients were positive for Piezo2, which is in accordance with the literature." (PMID 39001475, 2024). "This is the first study assessing Piezo2 expression in breast carcinoma employing clinical data from a cohort of patients." (PMID 39001475, 2024). "A cohort of 125 patients with clinical follow-up was chosen to study Piezo2 expression and clarify its clinical implications using the same immunohistochemical evaluation performed for other breast carcinoma parameters." (PMID 39001475, 2024). "To clarify the apparently opposing effects of Piezo2 channels and check their clinical relevance in breast cancer, we retrospectively chose a consecutive cohort of breast cancer patients undergoing surgery with a clinical follow-up of 5 years." (PMID 39001475, 2024). "In breast carcinoma, Piezo1 and Piezo2 were studied in various different cell lines, with positive expression in all of them." (PMID 39001475, 2024). "In contrast, Piezo2 is necessary for breast cancer cells to metastasize to the brain, as in the case of MDA-MB-231-BrM2 cells, because it acts as an upstream regulator of the RhoA-mDia pathway associated with invadosome functions." (PMID 37762011, 2023). "Meanwhile, analysis of the T dysfunction value in the core dataset suggested that Piezo2 played an important role in breast cancer (METABRIC) and endometrial cancer (TCGA)." (PMID 35991548, 2022). "In this study, we investigated PIEZO2’s roles in the breast cancer phenotype, using in vitro and in vivo experiments together with a bioinformatical approach." (PMID 36077309, 2022). "And hypomethylation of Piezo2 mediated a longer life span for breast cancer, bladder cancer, and kidney cancer patients and a shorter life span for brain cancer, stomach cancer, uveal cancer, and lung cancer patients." (PMID 35991548, 2022).
breast carcinoma (continued). "Utilizing PIEZO2 overexpressed breast cancer cells, and in vitro and in vivo experiments were conducted." (PMID 36077309, 2022). "We first investigated the impact of PIEZO2 mRNA expression level on breast cancer patients’ prognosis using a TCGA cohort." (PMID 36077309, 2022). "In other tumours, PIEZO2 knockdown in a breast cancer cell line (BrM2), inhibited the cells’ ability to enter confined spaces, but did not influence the speed of migration of the confined cells." (PMID 32228863, 2020). "The authors found that Piezo2 was frequently downregulated in a large panel of breast cancer cell lines and clinical samples." (PMID 32635333, 2020). "In conclusion, the present study confirmed that PIEZO2 expression in breast cancer was decreased and the downregulated expression of PIEZO2 indicated a poor prognosis of patients with breast cancer." (PMID 31058608, 2019). "Among all types of cancer, breast cancer presented as the highest expression value of PIEZO2 in both mRNA and protein levels." (PMID 31058608, 2019). "The prognostic roles of PIEZO2 in breast cancer patients according to various clinicopathological features were also determined by Kaplan Meier-Plotter database." (PMID 31058608, 2019). "In this study, we first detected the expression of PIEZO2 in all types of cancer, especially in breast cancer." (PMID 31058608, 2019). "We also investigated the prognostic role of PIEZO2 in breast cancer by PrognoScan, and the results demonstrated that breast cancer patients with low expression of PIEZO2 had a poor prognosis." (PMID 31058608, 2019). "Breast cancer patients with high expression of PIEZO2 had a significantly favorable prognosis, including overall survival, relapse free survival and distant metastasis free survival in both two probes." (PMID 31058608, 2019). "Subsequently, we confirmed that PIEZO2 was frequently downregulated in breast cancer cell lines and clinical samples relative to corresponding normal cell line and matched adjacent normal samples using qRT-PCR." (PMID 31058608, 2019). "All these findings suggest that PIEZO2 expression in breast cancer is significantly declined and negatively correlates with progression of breast cancer." (PMID 31058608, 2019). "The positive correlation of CDON expression with PIEZO2 expression in breast cancer was further determined by four databases, namely GEPIA, UALCAN, bc-GenExMiner and cBioPortal." (PMID 31058608, 2019). "Next, we determined the expression of PIEZO2 in breast cancer cell lines and clinical samples compared with normal breast cell line and matched non-cancerous samples." (PMID 31058608, 2019). "Relationship between PIEZO2 expression and prognosis in breast cancer patients (PrognoScan database)." (PMID 31058608, 2019). "Correlation between PIEZO2 expression and clinicopathological characteristics in TCGA breast cancer." (PMID 31058608, 2019). "Subsequently, we further studied the expression differences of PIEZO2 based on different clinicopathological parameters in breast cancer using bc-GenExMiner database." (PMID 31058608, 2019). "Subsequent analysis revealed that high expression of PIEZO2 had a favorable prognosis in breast cancer." (PMID 31058608, 2019). "By combination of expression and prognostic roles of these genes, CDON was thought to closely correlate with PIEZO2 in breast cancer." (PMID 31058608, 2019). "Using Kaplan Meier-Plotter, we found a favorable prognosis of PIEZO2 expression in breast cancer, especially in ER-positive, HER2-negative, luminal A and luminal B breast cancer." (PMID 31058608, 2019). "Then, the prognostic roles of PIEZO2 in breast cancer based on different clinicopathological features were assessed." (PMID 31058608, 2019). "Similarly, in breast cancer brain metastasis cells, PIEZO2 knockdown significantly reduces the expression levels of markers associated with cancer invasion and metastasis." (PMID 41327436, 2025).
breast carcinoma (continued). "Regarding Piezo2 expression in mammary gland neoplasms, a protective role for Piezo2 was initially suggested, but a subsequent study demonstrated a relationship between Piezo2 expression and the highly aggressive triple-negative phenotype of breast carcinoma." (PMID 39001475, 2024). "The apparent discordance between the studies regarding Piezo1 and Piezo2 correlation with aggressive phenotypes in breast neoplasms might be partly explained by the limited representativeness of the MCF-7 breast cancer cell line employed in the older study." (PMID 39001475, 2024). "However, opposing results regarding Piezo1 and Piezo2 roles in breast cancer exist in the literature." (PMID 39001475, 2024). "Interestingly, Piezo2 expression is also downregulated in breast cancer cell lines and patient tissue, and it negatively correlates with breast cancer progression." (PMID 37762011, 2023). "Indeed, Piezo1 and Piezo2 have recently been shown to enhance invadopodia formation in breast cancer cells." (PMID 36158191, 2022). "This study aimed to investigate PIEZO2’s role in breast cancer." (PMID 36077309, 2022). "Owing to the correlation between low Piezo2 expression and poor prognosis in breast cancer, believed that Piezo2 could be used as a prognostic indicator in breast cancer." (PMID 35991548, 2022). "Likewise, a previous study reported that decreased expression of Piezo2 predicted poor prognosis of patients with breast cancer." (PMID 35991548, 2022). "Previous research has been reported that miR-130b-3p present in exosomes contributes to CXCL12/CXCR4-induced colorectal cancer metastasis into liver and downregulate PIEZO2, thereby activating the Hedgehog signaling pathway and leading to worsening breast cancer prognosis." (PMID 33612479, 2021). "Piezo2 activates the RhoA signaling cascade to promote brain metastasis in breast cancer." (PMID 33806911, 2021). "Furthermore, the Piezo2 channel plays a role in laryngeal squamous cell carcinoma, bladder cancer, and breast cancer." (PMID 33935792, 2021). "The expression of Piezo2 has been ascertained in normal and breast cancer tissues." (PMID 32635333, 2020). "Overall, this study provides several evidences that Piezo2 downregulation might promote survival and progression of breast cancer." (PMID 32635333, 2020). "Furthermore, we also assessed the relationship between PIEZO2 expression and prognosis in breast cancer using PrognoScan database." (PMID 31058608, 2019). "Furthermore, we also found that high expression of PIEZO2 in basal-like breast cancer patients indicated a better prognosis in the probe 1562488_at." (PMID 31058608, 2019). "Altogether, these findings suggest that decreased expression of PIEZO2 may be utilized as a prognostic biomarker of breast cancer." (PMID 31058608, 2019). "UALCAN database analysis also revealed a low expression of PIEZO2 in breast cancer." (PMID 31058608, 2019). "Altogether, these findings suggest that low expression of PIEZO2 might be a promising prognostic biomarker in breast cancer." (PMID 31058608, 2019). "PIEZO2 expression level was positively correlated with distant metastasis free survival, relapse free survival, disease specific survival, disease free survival and overall survival in patients with breast cancer." (PMID 31058608, 2019). "Among these miRNAs, we found that five miRNAs (miR-130b-3p, miR-196a-3p, miR-301a-3p, miR-421 and miR-454-3p) possessed the greatest potential in targeting PIEZO2 in breast cancer by combination of correlation analysis, prognosis analysis, expression analysis and text mining." (PMID 31058608, 2019). "Therefore, we further assessed expression correlations between each predicted miRNA and PIEZO2 using TCGA breast cancer data." (PMID 31058608, 2019). "We hypothesized that PIEZO2 plays a significant role in breast cancer biology." (PMID 36077309, 2022).